EGFR (epidermal growth factor receptor)
Diseases named in the same sentence as EGFR in open-access papers (continued):
Sharing a sentence is not in itself a finding about the gene and the disease.
cervical carcinoma (continued). "Previously, using ChIP-seq analyses of H3K4me3 and H3K27AC, a “super enhancer” of EGFR was identified in cervical cancer cells." (PMID 34722266, 2021). "EGFR protein expression and gene amplifications have been correlated with unfavorable clinical outcomes and poor response to (C)RT in cervical cancer." (PMID 34830902, 2021). "Some evidence indicates that COX‐2 up‐regulation is dependent on EGFR in cervical cancer, but activated PAR2 can promote EGFR transactivation." (PMID 33369107, 2021). "Knockdown of c-Jun had similar effects, suggesting that JNK/c-Jun signalling regulated the expression of key EGFR signalling components in cervical cancer cells." (PMID 33303976, 2021). "A positive correlation between EGFR x uPA expressions (r=0.42, P<0.0001) and EGFR x TM expressions (r=0.51, P<0.0001) was observed in cervical cancer samples." (PMID 33886813, 2021). "To the best of our knowledge, we are the first to show this interplay between EGFR signaling and components of the fibrinolytic system in cervical cancer." (PMID 33886813, 2021). "For the small number of HPV-negative cervical cancers, over-activation of the PI3K/AKT/mTOR pathway or mutations of its regulatory factors, such as PTEN, EGFR, and HER2, accounted for the virus-independent etiology of carcinogenesis." (PMID 34589516, 2021). "Our results demonstrated that quercetin combined with cisplatin has a synergistic effect on cervical cancer, leading to decreased protein expression of EGFR, MYC, CCND1, and ERBB2." (PMID 35070983, 2021). "DNA from 46 cervical cancer tissue samples were extracted and amplified by PCR, using 1 set of primers designed for EGFR and 2 sets of primers designed for two different regions of both PIK3CA and KRAS gene." (PMID 33736612, 2021). "Meanwhile, it has also been reported that TGF-α and amphiregulin inhibit the Hippo signaling pathway and activate YAP through EGFR to induce the proliferation and migration of cervical cancer cells." (PMID 35070983, 2021). "EGFR, KRAS and PIK3CA genes were selected to be amplified in specific regions since these genes are implicated in most cancers, especially in cervical cancers." (PMID 33736612, 2021). "We also observed that EGFR signaling positively regulated expression of both uPA and TM in an aggressive cervical cancer cell line, and that uPA expression led to cell morphology alterations and increased migration." (PMID 33886813, 2021). "While data on the impact of the MAPK pathway are limited, numerous studies exist on EGFR signaling in cervical cancer." (PMID 34830902, 2021). "Twist1, one of the drivers of the EMT, was found to be elevated in hypoxia-treated cervical cancer (SiHa) cells, which increased their radioresistance, along with an increased nuclear EGFR localization and expression levels of nuclear DNA-PK." (PMID 33806538, 2021). "Aggressive human cervical cancer cells (CASKI) presented higher gene expression levels of EGFR, uPA, and TM compared to its less aggressive counterpart (C-33A cells)." (PMID 33886813, 2021). "In this study, we used E5-siRNA to knockdown that essential oncogene and considered the effect of E5 silencing on proliferation, apoptosis, cell cycle, apoptosis-related gene expression, and the initiator of the EGFR signaling pathway in cervical cancer cells." (PMID 37305401, 2021). "The positive crosstalk between the PAF-PAFR axis and EGFR demonstrates a relevant linkage between inflammatory and growth factor signaling in cervical cancer cells." (PMID 33392068, 2020). "In cervical cancer, a research group demonstrated that miR-2861 suppressed tumor cell growth and invasion by targeting EGFR/AKT2/CCND1 pathway." (PMID 32003757, 2020).
cervical carcinoma (continued). "Overall, these data suggested that GALNT7 played an important role in cervical cancer progression via EGFR/PI3K/AKT pathway." (PMID 32308562, 2020). "Cetuximab, an anti-epidermal growth factor receptor monoclonal antibody, is a standard option for the treatment of advanced cervical cancer." (PMID 32733542, 2020). "Atxn1 has been demonstrated to be involved in tumorigenesis of cervical cancer cells via the EGFR-RAS-MAPK signaling pathway." (PMID 32245399, 2020). "Human papillomavirus (HPV) 16 E6 has been proved to increase the radiosensitivity and lead to the EGFR overexpression in cervical cancer cells." (PMID 32850421, 2020). "Although the molecular mechanisms underlying this activity have not been fully elucidated, we reported in earlier studies Ct upregulation of host cell epidermal growth factor receptor (EGFR) signaling, a hallmark of cervical cancer." (PMID 33287170, 2020). "This positive crosstalk between the PAF-PAFR axis and EGFR demonstrates an important linkage between inflammatory and growth factor signaling in cervical cancer cells." (PMID 33392068, 2020). "PAFR- and EGFR-evoked signaling pathways contribute to tumor biology; however, the interplay between them remains uninvestigated in cervical cancer." (PMID 33392068, 2020). "It was observed a strong positive correlation between the expression of EGFR × PAFR and EGFR × LPCAT2 in 306 cervical cancer samples." (PMID 33392068, 2020). "Erlotinib is a small-molecule inhibitor of EGFR that has been shown to slow the growth of locally advanced cervical cancer." (PMID 32850421, 2020). "It has been reported that EGFR/PI3K/AKT pathway was one of the most enriched pathways involved in the development of cervical cancer, so we investigated the role of EGFR/PI3K/AKT pathway in the development of GALNT7-mediated cervical cancer." (PMID 32308562, 2020). "For instance, propofol enhanced the chemosensitivity to cisplatin‐induced apoptosis in cervical cancer cells through the epidermal growth factor receptor (EGFR)/JAK2/STAT3 pathway." (PMID 32596964, 2020). "EGFR ligands such as amphiregulin and TGFα were upregulated by IL-6 via an EGFR-dependent pathway of autocrine stimulation in human cervical carcinoma cells and virus-immortalized cells." (PMID 32709896, 2020). "Recent studies, including ours, have demonstrated that the overexpression of EGFR negatively impacts the overall survival of cervical cancer patients and the response to chemoradiation." (PMID 33392068, 2020). "Altogether, E5 oncoprotein activates EGFR, which enhances YAP leading to the upregulation of PD-L1, thus initiating T cell apoptosis and persistent HPV infections and augmenting the risk of cervical cancer development." (PMID 32695664, 2020). "The literature has shown that EGFR is expressed in about 80% of cervical carcinomas and is correlated with disease progression." (PMID 33392068, 2020). "Apart from both in vitro and in vivo data supporting a critical role of EGFR in MUC1-mediated paclitaxel-resistance, our clinical study showed elevated expression of MUC1, EGFR, and IL-6 in post-chemotherapy cervical cancer tissues." (PMID 31772161, 2019). "EGFR, NOTCHI, RHOA and other genes are associated with the lymph node metastasis of cervical cancer." (PMID 31744495, 2019). "HPV16 is linked to cervical cancer development, and EBP50 has been shown to be downregulated in HPV16-positive cervical premalignant lesions and in cervical cancer-derived cell lines, concomitant with EGFR activation." (PMID 29846905, 2019). "Activation of YAP1 in cervical cancer cells significantly stimulated the expression of EGFR and its ligands TGFα and AREG." (PMID 30840887, 2019). "More importantly, positive correlations between the expressions of MUC1, EGFR, and IL-6 were found in 20 cervical cancer patients after chemotherapy." (PMID 31772161, 2019). "Here, we reveal that EGFR correlates with reduced disease-free survival in cervical cancer patients with chemotherapy." (PMID 31772161, 2019).
cervical carcinoma (continued). "Consistent with the finding that KP can suppress EGFR activation, KP has been proven to possess anti-proliferative properties against HeLa cervical cancer cells." (PMID 31470515, 2019). "In cervical cancer, a phase II clinical study with EGFR inhibitor Erlotinib showed that administering it prior to receiving the standard of treatment (cisplatin concurrent with radiotherapy) was safe and showed significant antitumor activity." (PMID 30760827, 2019). "In the current study, we report that EGFR is transactivated by PAR2 agonists in cervical cancer cells, promoting resistance to cisplatin through a COX2-dependent mechanism." (PMID 30093972, 2018). "In cervical cancer patients, PAR2, as well as EGFR and COX2, was independently associated with poor prognosis." (PMID 30093972, 2018). "Previous reports have shown that EGFR is expressed in 80% of cervical carcinomas and is correlated with disease progression." (PMID 30093972, 2018). "Herein we employed cervical cancer cell lines and The Cancer Genome Atlas (TCGA) database to evaluate the role of EGFR, TF and PAR2 in chemoresistance." (PMID 30093972, 2018). "We conclude that acute exposure to tobacco smoke activates the transcription of HPV16 E6 and E7 oncogenes through p97 promoter activation, which involves the EGFR/PI3K/Akt/C-Jun signaling pathway activation in cervical cancer cells." (PMID 30619121, 2018). "Our observation that the high expression of EGFR predicted poor survival in cervical cancer has been confirmed in a previous report." (PMID 30445744, 2018). "EGFR (Epidermal Growth Factor Receptor) is an oncogene overexpressed in cervical cancer that is involved in chemoresistance." (PMID 30093972, 2018). "Herein, we observed that cervical cancer cells display enhanced TF mRNA levels upon activation of EGFR." (PMID 30093972, 2018). "We also showed a strong correlation between EGFR and TF expression levels in 309 TCGA samples of cervical cancer." (PMID 30093972, 2018). "CD73 promotes cervical cancer cell proliferation and migration, via potentiating EGFR/Akt and VEGF/Akt pathways." (PMID 30514403, 2018). "Preclinical data from our group showed that the EGFR signaling pathway mediates resistance to chemoradiation in cervical cancer cells." (PMID 30093972, 2018). "Cervical cancer is often associated with HPV infection and intriguingly, HPV 16 E5 gene has been observed to increase the expression of EGFR by preventing the degradation of internalized EGFR44." (PMID 29777148, 2018). "SkQ1 inhibited mtROS in the cells overexpressing p66shc so downregulation of EGFR signaling in cervical cancer cells was probably mediated by inhibition of p66shc-dependent mtROS production." (PMID 27902484, 2017). "The epidermal growth factor receptor (EGFR) has been found to be overexpressed in 70%–90% of cervical cancer cases." (PMID 29212253, 2017). "Data indicated that cetuximab combined with chemoradiation, trastuzumab, or MAPK inhibitors is useful for cervical cancer treatment, independently of EGFR expression." (PMID 30410707, 2017). "To study the role of EGFR signaling in cervical cancer cells we stimulated EMT progression with exogenous EGF." (PMID 27902484, 2017). "EGFR activation is a common contributor to malignancy, and many reports have implicated increased EGF signaling as a driver of both ovarian and cervical cancer." (PMID 28640887, 2017). "Epidermal growth factor receptor (EGFR) is overexpressed in 70% to 90% of analyzed cervical cancer cases." (PMID 27902484, 2017). "Since we have also observed that cyclin G2 can exert potent anti-tumorigenic effects, it is possible that inhibition of cyclin G2 by EGFR is a significant event underlying the oncogenic actions of EGF and contributes to ovarian and cervical cancer development." (PMID 28640887, 2017).
cervical carcinoma (continued). "Immunofluorescent study of surgical specimens indicated that cervical carcinoma progression was accompanied by EGFR overexpression and decreased E-cadherin content that correlated with Snail upregulation." (PMID 27902484, 2017). "Ten cervical cancer cell lines (EGFR-expressing except for C33A, and all RASwt) were subjected to PBNK only, CET only, or to a combination of PBNK with CET in order to examine ADCC effects." (PMID 27783105, 2017). "Other subgroup analyses performed by quality rating score, histological type, number of patients, publication year, study design, and study location also revealed associations between high EGFR levels and poor DFS in cervical cancer patients." (PMID 27438047, 2016). "The present study demonstrates GW627368X, a highly selective competitive EP4 antagonist, which hinders cervical cancer progression by inhibiting EP4/epithelial growth factor receptor (EGFR) interactive signaling." (PMID 27010855, 2016). "EGFR expression seems to have an important role in tumor angiogenesis and has been used for the detection and treatment of advanced cervical cancer." (PMID 26881213, 2016). "Most of studies on the ligand-induced endocytosis and degradation of EGFR have been characterized in cervical cancer HeLa cells." (PMID 27034618, 2016). "In these abnormal contexts, MIR133b in human cervical carcinoma targets EGFR and FGFR1, similarly acting as a tumor suppressor." (PMID 27471470, 2016). "Subgroup analyses demonstrated that EGFR overexpression was related to poor DFS in cervical cancer patients who were treated with chemoradiation (HR: 1.69, 95% CI: 1.32–2.15) and surgery (HR: 2.02, 95% CI: 1.37–2.96)." (PMID 27438047, 2016). "Our studies have shown that both chemical and physical stress conditions induce endocytosis and degradation of EGFR in cervical cancer HeLa cells." (PMID 27034618, 2016). "We also demonstrated that overexpression of miR-2861 resulted in the suppression of EGFR/AKT2/CCND1 pathway in cervical cancer cells." (PMID 27364926, 2016). "Several studies reported that EGFR was overexpressed in cervical biopsies of cervical cancer patients." (PMID 26881213, 2016). "Recently reports showed that EGFR was overexpressed in cervical biopsies of cervical cancer patients." (PMID 26881213, 2016). "To elucidate the regulatory mechanisms of miR-2861 in cervical cancer, we identified, for the first time, EGFR, AKT2, and CCND1 as the targets of miR-2861 in both SiHa and CaSki cells." (PMID 27364926, 2016). "Our results thus indicated that GW627368X hindered proliferation and induced apoptosis in cervical cancer cells via the cyclic adenosine monophosphate/PKA/CREB as well as pathway involving EGFR/Ras/MAPK/CRB and Akt/GSK3β/ β-catenin." (PMID 27010855, 2016). "This was not the case (unselected population) in other early clinical trials combining the epidermal growth factor receptor (EGFR) inhibitor cetuximab with CRT in cervical cancers." (PMID 27016411, 2016). "Further analysis revealed that both studies reported a favorable trend for cervical cancer patients with EGFR overexpression." (PMID 27438047, 2016). "Previous studies have shown that treatments of anisomycin or UV irradiation with cervical cancer HeLa cells induced degradation of EGFR." (PMID 27034618, 2016). "QDs with the EGFR antibodies as labeling probes were successfully applied to targeted imaging for EGFR on the surface of SiHa cervical cancer cells through conjugation of QDs with the anti-EGFR antibodies." (PMID 25897311, 2015). "The present study provides compelling evidence showing that the HPV E6 protein, the Hippo pathway, and the EGFR signaling pathway interact with each other to regulate cervical cancer progression." (PMID 26417066, 2015).
cervical carcinoma (continued). "Activated YAP allows for up-regulation of TGF-α, AREG, and EGFR, forming a positive signaling loop to drive cervical cancer cell proliferation." (PMID 26417066, 2015). "The present study shows for the first time that nuclear translocation of EGFR can be induced by the soluble form of HB-EGF in human cervical cancer A431 cells." (PMID 26016774, 2015). "The experiment aimed to confirm that anti-EGFR/HGNs can be selectively localized around the cytoplasmic membrane of cervical cancer cells to promote HGN entry into tumor cells by both active and passive targeting." (PMID 25995714, 2015). "This evidence suggests that YAP and EGFR proteins are continuously synthesized and degraded in a proteasome-dependent mechanism in cervical cancer cells." (PMID 26417066, 2015). "Secondly, both TGF-α and AREG dephosphorylate MOB1, LATS1, and YAP in cervical cells (Figs6 and 7), suggesting that the Hippo pathway is actively involved in the EGFR pathway regulation of cervical cancer progression." (PMID 26417066, 2015). "Our study suggested that somatic mutations in EGFR, FGFR2, and FGFR3 are rare in cervical cancers; this result was similar to the findings of previous studies." (PMID 25669975, 2015). "Collectively, these data provide evidence for an association between EGFR, COX-2, and VEGF expressions in cervical cancer tumor angiogenesis and tumor growth." (PMID 24860830, 2014). "We showed here that Semaphorin 3A relies on KIAA1199 to transiently trigger EGFR phosphorylation in cervical cancer cells." (PMID 25366117, 2014). "In particular, the combination of COX-2 inhibitors and EGFR-inhibitors seems to increase the therapeutic effect in colon or cervical carcinoma." (PMID 24934485, 2014). "A number of biological molecules modulate angiogenesis in cervical cancer such as epidermal growth factor receptor (EGFR), cyclooxygenase-2 (COX-2), and vascular endothelial growth factor (VEGF)." (PMID 24860830, 2014). "Nevertheless, in cervical cancer, that presents an EGFR over-expression, EGF has been shown to be one of the most potent inducers of EMT and associated with cervical stromal invasion and nodal metastasis." (PMID 25058589, 2014). "So far, only a few small-scale clinical trials have been tested to evaluate the efficacy of EGFR inhibitors for the treatment of cervical cancer." (PMID 23936413, 2013). "It is evident that EGFR is expressed in normal and cervical cancers with varying degrees of EGFR expression." (PMID 24843386, 2013). "Although mutations in EGFR in high-grade invasive cervical cancer are rare, it would be important to study an association between TACC3 expression and EGFR mutations." (PMID 23936413, 2013). "EGFR is present in numerous normal tissues and is expressed in a wide variety of solid tumors, including cervical cancer." (PMID 24843386, 2013). "To date, dominant therapeutic targets under scrutiny for cervical cancer treatment have been EGFR pathway and angiogenesis inhibition as well as anti-HPV vaccines." (PMID 22091418, 2011). "Antibodies against Vascular Endothelial Growth Factor (VEGF) and Epidermal Growth Factor Receptor (EGFR) have been used in different neoplasms such as ovarian and cervical cancer." (PMID 22235224, 2011). "A431, a vulvar carcinoma cell line, strongly expresses EGFR, while the cervical carcinoma Caski and C33A cell lines showed moderate and low expression levels of this receptor." (PMID 22185378, 2011). "A functional assessment was performed by inactivating EGFR in cervical cancer cells with the potent inhibitor AG1478." (PMID 21730982, 2011). "At this stage the three dominant targets under scrutiny for innovative cervical cancer treatments are the EGFR pathway, angiogenesis inhibition, and anti-HPV vaccines." (PMID 22091418, 2011). "Larger, prospective studies are required to definitively establish an effect of EGFR overexpression on cervical cancer prognosis." (PMID 21730982, 2011).